INS (insulin)
Diseases named in the same sentence as INS in open-access papers (continued):
Sharing a sentence is not in itself a finding about the gene and the disease.
Insulin resistance (continued). "Insulin tolerance test (ITT) showed that despite the overall lower insulin levels CF rabbits at this age do not suffer from insulin resistance." (PMID 36712930, 2023). "There was a moderate and significant negative association between the insulin sensitivity marker SPISE and the insulin resistance markers HOMA-IR (R = −0.49) and QUICKI-IR (R = −0.55)." (PMID 36677025, 2023). "Regarding cross-sectional associations in the early postpartum, CRP correlated with higher weight and body fat, increased insulin resistance (higher HOMA-IR and lower MATSUDA), absolute insulin secretion (HOMA-B and AUCins/glu) and reduced relative insulin secretion (ISSI-2) (all p ≤ 0.009)." (PMID 37891561, 2023). "Both insulin levels and HOMA-IR are indicators of insulin resistance." (PMID 36800965, 2023). "Intriguingly, in our model, HC treatment resulted in mild insulin resistance typified by elevated plasma insulin levels, especially in female mice, with no real alteration of glucose homeostasis." (PMID 37650517, 2023). "In addition, insulin activates the group I p21-activated kinase (PAK) isoforms PAK1 and PAK2, and PAK1/2 signaling was impaired by insulin resistance in skeletal muscle." (PMID 36942499, 2023). "We have recently demonstrated that male mice lacking Slc12a2 in insulin-secreting β-cells develop overweight, hyperlipidemia, glucose intolerance, insulin resistance, and steatohepatitis spontaneously without overeating." (PMID 37819196, 2023). "Myotubes from affected women, however, show innate flaws in insulin signalling and glucose transport, including elevated phosphorylation of IRS-1 Ser312, which may increase vulnerability to factors that promote insulin resistance." (PMID 36751233, 2023). "Importantly, although insulin-resistant adipocytes have been shown to increase expression of TNF-α, IL-6, and IL-8, only IL-6 released into the systemic circulation induces insulin resistance in the liver and the production of C-reactive protein." (PMID 37664841, 2023). "Additionally, it improves carbohydrate metabolism, with fasting glucose decreasing by 14.6%, postprandial glucose by 19.1%, insulin by 2.3 times, and HOMA-IR index by 2.35 times, indicating reduced insulin resistance." (PMID 37438785, 2023). "In contrast, despite insulin resistance and high insulin levels, cafeteria feeding did not change the insulin‐mediated drop in glucose as some glucose homeostasis parameters did not change in CAF." (PMID 37970433, 2023). "It is known that disturbance of insulin secretion rather than insulin resistance is the main mechanism for the development of PTDM in the early stages of transplantation." (PMID 37424863, 2023). "Ang II inhibits the insulin-induced activation of the PI3K pathway, leading to a reduction in endothelial nitric oxide (NO) production and Glut-4 translocation in insulin-sensitive tissues, resulting in insulin resistance." (PMID 38025203, 2023). "Evidence supports the concept that, even in the presence of insulin resistance, adipocytes tend to maintain their sensitivity to insulin, unlike muscle and liver cells." (PMID 37899888, 2023). "It is categorized into type 1 diabetes (absolute lack of insulin) and type 2 diabetes (T2DM, insulin resistance or relative lack of insulin)." (PMID 37888727, 2023). "Also, upregulation of miR-223-3p increases insulin resistance through upregulation of Glucose transporter type 4 (GLUT4) protein, the major regulator of insulin-mediated glucose translocation into the adipocytes." (PMID 36869348, 2023). "In a cohort of middle-aged men, elevated fasting levels of acetoacetate were associated with incident type 2 diabetes during a 5-year follow-up and with impaired insulin secretion rather than insulin resistance." (PMID 36961590, 2023). "In addition, insulin sensitivity and insulin resistance were quantified using QUICKI and HOMA-IR, respectively, which are both based on fasting levels of circulating glucose and insulin." (PMID 37935669, 2023).
Insulin resistance (continued). "It is important to remember that weight gain increases insulin resistance but does not have a direct effect on insulin secretion." (PMID 37795366, 2023). "Insulin resistance (IR) is an alteration of the action of insulin in cells, which do not respond adequately to this action, leading to an increase in blood glucose levels." (PMID 38140381, 2023). "Selective hepatic insulin resistance impairs the ability of insulin to suppress glucose production but not its ability to activate lipogenesis." (PMID 36928190, 2023). "Actually, CVDs seem to be more conditioned by insulin resistance, which (due to the lack of insulin-mediated inhibition) stimulates the release of free fatty acids (FFAs) from the adipose tissue." (PMID 38067472, 2023). "Insulin resistance, a complicated metabolic reaction, was commonly estimated using absolute fasting glucose values and insulin values, without taking into account the adipose tissue specificity of insulin resistance." (PMID 38041145, 2023). "GPER expression is strongly increased in tissues from EC patients with insulin resistance and also positively correlates with TET1 expression in EC tissues, which further indicate the role of insulin in the progression of EC mediated by TET1-driven GPER expression." (PMID 36750868, 2023). "In contrast, some researchers have suggested an association between antioxidant-rich diets and atherosclerosis, but not with insulin, insulin resistance, or total cholesterol." (PMID 37637947, 2023). "Conversely, PTP-1B−/- mice show enhanced glucose tolerance and increased systemic insulin sensitivity, indicating that PTP-1B may serve as a potential therapeutic target for improving insulin resistance." (PMID 38053837, 2023). "Moreover, insulin increases SELS expression in cultured adipocytes, suggesting a potential feed-forward mechanism for increased SAA expression in insulin resistance." (PMID 37396595, 2023). "While a degree of insulin resistance is a physiological adaptation in late gestation, in GDM, significant impairments can occur in downstream insulin signalling in WAT (e.g., decreased insulin receptor-β (IR-β) phosphorylation, downregulation of IRS1 and signalling through PI3K)." (PMID 36836658, 2023). "Insulin resistance is the cornerstone of NAFLD development, and the decline in insulin sensitivity in peripheral tissues, particularly accompanied by elevated compensatory hyperinsulinemia, promotes the uptake of free fatty acids by the liver and lipogenesis, leading to steatosis." (PMID 36978847, 2023). "In this patient group, insulin resistance is not emphasized in daily practice and insulin, glucose and blood lipid levels are not among the parameters recommended to be followed routinely." (PMID 35765946, 2023). "Fifth, there was no serum insulin data in the present study; therefore, another method to evaluate insulin resistance, like HOMA-IR deserves other studies for clarification." (PMID 37316697, 2023). "In addition, the Homeostasis Model Assessment of Insulin Resistance (HOMA-IR) and Quantitative Insulin Sensitivity Check Index (QUICKI) were calculated." (PMID 37752490, 2023). "Conversely, the inhibition of PTP1B in diet-induced obesity animals potentially improved insulin resistance and normalized plasma glucose and insulin levels without inducing hypoglycemia." (PMID 37383489, 2023). "Short-term fructose consumption, in isocaloric exchange or in hypercaloric supplementation, promotes the development of hepatic insulin resistance in nondiabetic adults without affecting peripheral or muscle insulin sensitivity." (PMID 36673104, 2023). "They found one cluster which was insulin-dependent, with low BMI and poor metabolic control (similar to cluster 1); and other two clusters with higher onset age, no insulin resistance and with obesity (similar to clusters 3 and 4)." (PMID 37647301, 2023).
Insulin resistance (continued). "When insulin resistance develops, liver, muscle and adipose cells do not respond to insulin, and blood glucose concentration increases." (PMID 36834911, 2023). "The review found that hesperidin did not have a significant effect on fasting blood glucose, insulin, or homeostatic model assessment of insulin resistance (HOMA-IR)." (PMID 37502716, 2023). "Barzegari et al29 and Esfandiari et al30 reported a decreased fasting blood sugar (FBS) and Homeostatic Model Assessment for Insulin Resistance (HOMA-IR) in the vitamin D group at study end, as well as a reduction in insulin levels that approached significance (P = .07)." (PMID 38033482, 2023). "In response to a challenge injection of insulin, the HFD-fed rats displayed higher glucose levels than RD controls, suggesting that our feeding regimen combined with administration of a low dose of STZ induced insulin resistance." (PMID 38389818, 2023). "The relationship between DhCer and insulin resistance may be causative, since a recent study reported that the delivery of DhCer carried in liposomes into skeletal muscle cells counteracts the stimulating effect of insulin on glycogen synthesis, without affecting cellular Cer levels." (PMID 37143040, 2023). "However, in another palmitic-acid-induced insulin-resistance model, FGF21 still plays an important role in improving insulin signaling, but with the help of other molecular regulation." (PMID 38069273, 2023). "Insulin resistance occurs when insulin fails to sufficiently stimulate glucose uptake in muscle and inhibit hepatic glucose production." (PMID 37065747, 2023). "In addition, blood insulin levels appear to decrease in the LPS (+) group compared with those in the LPS (−) group, and HOMA-IR, a marker of insulin resistance, decreased significantly in the LPS (+) group compared with that in the LPS (−) group." (PMID 36902049, 2023). "In addition, FGF21 normalized the plasma insulin and Homeostatic Model Assessment for Insulin Resistance index, indicating that FGF21 restores insulin sensitivity to that observed in LFCD-fed mice." (PMID 36648330, 2023). "At the time of writing, there were not many studies on the correlation between insulin function, insulin resistance indexes, and GBS in newly diagnosed T2DM patients." (PMID 37893213, 2023). "Insulin resistance and insulin sensitivity are recognized as negative and positive symptoms, respectively, in common clinical practice." (PMID 38003366, 2023). "We began our investigation by assessing the effect of JPH both with and without insulin resistance on both basal and insulin-stimulated pAkt expression." (PMID 37367923, 2023). "First, insulin resistance has been observed without decreased phosphorylation of Akt at its activating phosphosites in diverse models of insulin-resistant 3T3-L1 adipocytes and L6 myotubes, and human muscle ex vivo and in vivo." (PMID 37248992, 2023). "Insulin resistance: Hispanic individuals are more insulin resistant than non-Hispanic whites (NHWs), putting them at a higher risk of developing T2DM." (PMID 36835260, 2023). "Chronic inflammation in insulin‐responsive target tissues is accompanied by ROS levels elevation and, consequently, the stress‐related signaling pathways such as JNKs, PKC, GSK3, NF‐kB, and P38 were activated and eventually accelerate insulin resistance." (PMID 37329278, 2023). "More recent publications by other groups also reported that miR-152 targets SOCS3 to inhibit hepatic insulin resistance in mice with gestational diabetes and that miR-148 silencing in MIN-6 β-cells and mouse islets downregulates insulin promoter activity and expression." (PMID 36869830, 2023). "Clinically, the progressive nature of T2D is linked to beta cell dysfunction and loss, with patients lacking the ability to produce sufficient endogenous insulin to counteract insulin resistance and to control blood glucose levels." (PMID 37813862, 2023).
Insulin resistance (continued). "To determine how aM1 alleviates insulin resistance, we profiled the transcriptome of insulin-resistant C2C12 myotubes treated with or without aM1." (PMID 37715850, 2023). "This reduction in liver 11β-HSD1 may account for partial impairment of the insulin signaling pathway in the liver in the present study, once overexpression of 11β -HSD1 in the liver in mice results in insulin resistance." (PMID 37234421, 2023). "Analysis of metabolic parameters showed that HFD fasting glycemia, insulin concentration, and HOMA index were more elevated than in Lean mice, indicating an impairment of glucose metabolism and insulin resistance condition, which was lightly improved by AFA consumption." (PMID 36902167, 2023). "Fourth, the HOMA-IR value, which is another well-known insulin resistance surrogate, cannot be included due to the absence of serum insulin level." (PMID 37563268, 2023). "Altogether, these results indicate that VFP and VFPE attenuate whole-body glucose intolerance, insulin resistance, and VFPE, specifically decreasing excessive insulin secretion from the pancreas, preventing hyperinsulinemia and pancreatic islet hypertrophy in mice fed an HF diet." (PMID 37175691, 2023). "The prediction of absolute insulin secretion by CRP is most likely related to the observed increase in insulin resistance, which was independent of weight and partly of body fat." (PMID 37891561, 2023). "While SKO-001 had little effect on plasma glucose levels compared with the HFD group, plasma insulin levels were markedly reduced by SKO-001 treatment, suggesting that SKO-001 may improve insulin resistance developed by chronic HFD feeding." (PMID 36729332, 2023). "Lower values of QUICKI may indicate greater insulin resistance, and high HOMA-IR values indicate low insulin sensitivity." (PMID 37752490, 2023). "Nevertheless, recent data showed that increased HMGB1 may impair insulin signaling in granulosa cells obtained from PCOS patients, suggesting that both directions in the relationship between HMGB1 and insulin resistance are potentially working." (PMID 37256493, 2023). "In clinical studies, premenopausal women when compared to women after menopause and the respective age-matched men, are characterized by higher insulin sensitivity assessed by homeostatic model assessment–insulin resistance (HOMA-IR) and adipose-insulin resistance index." (PMID 36979669, 2023). "Insulin resistance itself does not result in the conversion to T2D because impaired insulin secretion is always needed to generate hyperglycaemia." (PMID 37795366, 2023). "In most studies, GLP-1 levels were not related to insulin concentration or measures of insulin resistance." (PMID 37445623, 2023). "High intakes of milk, but not meat, increase serum insulin and insulin resistance, as shown in 8-year-old boys." (PMID 37998335, 2023). "As expected, we observed a negative trend in respiratory quotient, while fasting insulin and insulin resistance were found to decrease significantly after cKD initiation." (PMID 37293674, 2023). "In addition, indicators such as homeostasis model assessment insulin resistance (HOMA-IR) and insulin levels can evaluate the status of insulin sensitivity and insulin secretion function, which is helpful for further diagnosis and treatment of GMD." (PMID 37822878, 2023). "Insulin resistance refers to a condition in which insulin signaling is blocked, and cells do not respond to the normal action of insulin." (PMID 38203517, 2023). "Insulin resistance (IR) is a condition in which cells show diminished response to insulin regardless of hyperinsulinemia." (PMID 37424876, 2023). "Compared with women with PCOS without insulin resistance, those with insulin resistance display greater β-cell function, which is compatible with their ability to maintain higher circulating insulin levels." (PMID 37251667, 2023).
Insulin resistance (continued). "To evaluate glucose tolerance, we calculated homeostasis model assessment estimated insulin resistance (HOMA-IR) calculations, a measure of insulin resistance, and homeostasis model assessment of β-cell function (HOMA-β) calculations, a measure of basal insulin secretion." (PMID 38117787, 2023). "Insulin resistance is a defining characteristic of type 2 diabetes, whereby the cells in the body do not adequately respond to insulin signals, resulting in impaired glucose uptake." (PMID 37881393, 2023). "Paternal DCHP exposure led to exacerbated insulin resistance and impaired insulin signaling in F1 offspring without affecting diet-induced obesity." (PMID 36709676, 2023). "Moreover, relevant pathways related to type I diabetes mellitus (PTPRN2), insulin resistance (RPS6KA2), and insulin secretion (ADCYAP1R1) were also identified." (PMID 37415231, 2023). "The increase in insulin levels was supported by a negative correlation between BMI and insulin sensitivity in one study, and increased insulin resistance in overweight/obese women compared to women of normal weight in another study." (PMID 36520252, 2023). "In the context of obesity and type 2 diabetes, metabolic and inflammatory stress increase the activities of JNK and ERK in insulin target tissues, and these kinases induce serine phosphorylation of IRS1 or IRS2, whereas uncontrolled IRS serine phosphorylation promotes insulin resistance." (PMID 37108143, 2023). "The properties of vitamin D in insulin-sensitivity modulation were recently confirmed by the inhibition of the expression of peroxisome proliferator-activated receptor Υ (PPAR-Υ) and reducing peripheral insulin resistance." (PMID 38084240, 2023). "The top-weighted traits included increased hepatic enzymes (aspartate aminotransferase [AST], alanine aminotransferase [ALT], γ-glutamyl transferase [GGT]), increased Homeostatic Model Assessment for Insulin Resistance (HOMA-IR), and decreased insulin sensitivity index." (PMID 37886436, 2023). "The implications for neural-level insulin resistance and MDD are clear considering findings that obese humans show neural unresponsiveness to exogenous insulin and fail to show mood elevating effects observed in normal-weight humans resulting from a course of intranasal insulin administration." (PMID 37208333, 2023). "DM occurs mostly in the context of β-cell dysfunction and insulin resistance due to the feedback loop between insulin action and insulin secretion not working properly." (PMID 36830642, 2023). "Results from Qatari patients with severe insulin resistance showed that these patients did not respond adequately to insulin sensitizers such as metformin." (PMID 37626661, 2023). "Studies of insulin resistance have shown that the relationship between insulin sensitivity and insulin release is non-linear, with a shape representative of the positive quadrant of the cosecant hyperbolic curve." (PMID 37745252, 2023). "Conversely, women who gained weight during the study period exhibited an increase in insulin resistance, without a compensatory rise in insulin secretion." (PMID 37903900, 2023). "Han and Bonen reported that both insulin and epinephrine increase GLUT4 expression on the plasma membrane, but when their concentration is high at the same time, epinephrine reduces the carrying capacity of GLUT4, inducing insulin resistance." (PMID 37842314, 2023). "During obesity, lipotoxicity, chronic inflammation, hyperglycemia, hyperinsulinemia, mitochondrial dysfunction, and ER stress stimulate the activity of Ser/Thr kinase and impair insulin sensitivity by phosphorylating IR, IRS, and AKT proteins, resulting in insulin resistance." (PMID 37960324, 2023). "These MAIT cells may have been contributing to insulin resistance, as MR1-/- mice had greater insulin sensitivity to oral insulin tolerance testing." (PMID 36911683, 2023).